VIM (vimentin)
Diseases named in the same sentence as VIM in open-access papers (continued):
Sharing a sentence is not in itself a finding about the gene and the disease.
tumor (continued). "In our cohort, CD27 expression was restricted to the TME, showing coexpression with vimentin + CAFs, CD3 + T-cells, and a moderate number of CD68 + TAMs in the stroma and tumor nests." (PMID 40205178, 2025). "Consistently, TCF1OE tumours formed robust organoids ex vivo and co-expressed CD104/CD44 with E-cad/VIM as compared to control tumours." (PMID 40764669, 2025). "Further examination of the DEPs revealed that several signaling molecules previously identified at the tumor boundary, including ITGB4, COL1A2, and VIM, were significantly upregulated in the cancer-adjacent tissue (p.adjust < 0.05)." (PMID 40725477, 2025). "It induced immunogenic cell death (ICD) characterized by calreticulin exposure and ATP release, while modulating the tumor microenvironment by downregulating MMP-3, MMP-9, VEGF, and vimentin, and restoring epithelial markers." (PMID 41304785, 2025). "Immunohistochemistry (IHC) staining of patient tumor sections and immunofluorescence (IF) staining of organoid sections for CD99, VIM, CD68, KI67, and SATB2 showed positive expression in both, confirming histopathological similarities." (PMID 40476445, 2025). "Further analysis of the tumor cells displayed positivity for smooth muscle actin (SMA) and vimentin, reflecting the modified smooth muscle origin of the glomus cells." (PMID 40225461, 2025). "Immunohistochemically, the tumor was positive for the epithelial markers AE1/AE3 and the mesenchymal marker vimentin, suggesting carcinosarcoma." (PMID 40527829, 2025). "In the context of oncology, Vimentin is widely recognized as a mesenchymal marker and is strongly upregulated during epithelial-mesenchymal transition (EMT), a process critical to tumor invasion and metastasis." (PMID 41018072, 2025). "Immunohistochemical examination identifies specific tumor cell markers, such as Vimentin, SMA, Desmin, etc., which assist in determining the tumor type and origin." (PMID 40746595, 2025). "The tumor cells frequently express cytokeratin AE1/AE3, low-molecular-weight cytokeratin, vimentin, cyclin D1, hypoxia-inducible factors (HIF), and VEGF." (PMID 41497945, 2025). "The PTO microenvironment was characterized and compared with the in vivo tumor using immunohistochemical and immunofluorescence staining for alpha-smooth muscle actin (α-SMA) and vimentin." (PMID 41035875, 2025). "Given the pivotal role of EMT remodeling in tumor metastasis, we next interrogated the impact of GPR174 on EMT biomarker expression (E-cadherin, N-cadherin and vimentin) within hepatic metastasis models." (PMID 40229851, 2025). "Immunohistochemistry in our patient confirmed CK20 (+), CK8/18 (+), EMA (+), GATA-3 (+), and vimentin (+), and the patient’s Ki-67 (+, about 60%), and CD10 (partially +) indicated that the tumor was highly malignant and aggressive." (PMID 40083878, 2025). "Immunohistochemical analysis revealed weak positivity for epithelial membrane antigen (EMA) in some tumor cells, with diffuse expression of somatostatin receptor 2 (SSTR2) and vimentin." (PMID 41013491, 2025). "Based on the results obtained with this model, the vimentin+ EMT cells are highly proliferative cells and their ablation inhibits tumor growth at primary and metastatic sites." (PMID 40301945, 2025). "Both M10 and M02 tumor cells expressed markers consistent EMT transition such as N-cadherin and vimentin for M10, and vimentin and snail for M02." (PMID 41413213, 2025). "IF1 expression levels were positively related to those of VE-cadherin, vimentin, MMP2, and MMP9, while they were negatively related to E-cadherin, indicating that IF1 can promote tumor progression by enhancing the EMT and VM formation." (PMID 41306771, 2025). "So, based on these assumptions, this study highlights the central role of oxidative stress in the pathogenesis of LSCC, focusing on the expression of six key proteins involved in antioxidant defense and tumor biology: SOD, CAT, HO-1, NRF-2, MT, and VIM." (PMID 40149643, 2025).
tumor (continued). "Our data established PBRM1 as a tumor suppressor that controls tumor grade and metastasis of PDAC by regulating vimentin expression." (PMID 40454484, 2025). "Tumor cells exhibited weak EMA expression and focal positivity for PR, with strong, diffuse staining for SSTR2 and vimentin." (PMID 41013491, 2025). "Western blot analysis of tumor tissues from nude mice showed that SPON2 knockdown significantly increased E-cadherin levels while reducing the expression of N-cadherin, Vimentin, NF-κB p65, and VEGF, indicating a suppression of EMT." (PMID 40730813, 2025). "In contrast to E‐cadherin, β‐catenin, fibronectin, vimentin, and N‐cadherin are four key proteins that are upregulated during the process of EMT, which is a critical step in tumor progression and metastasis." (PMID 40650414, 2025). "As for the IHC, the tumor cells were positive for α-SMA, MSA, h-caldesmon, calponin, vimentin and collagen IV." (PMID 40255432, 2025). "Pathologically, tumor cells are perivascular pseudorosettes, presenting immunoreactivity for GFAP, S-100, Vimentin, “dot-like” staining for EMA, and low proliferative activity." (PMID 39098857, 2025). "Low expression of RORα leads to high circulating tumor cell count and up-regulation of VEGF in GC, while silencing RORα can significantly promote the proliferation, up-regulate N-cadherin and Vimentin, and down-regulate E-cadherin." (PMID 41425709, 2025). "The differences in the marker levels between tumor and normal specimens were statistically significant for all markers except for CD44S and Vimentin." (PMID 40149256, 2025). "Western blot analysis of tumor tissues confirmed that fedratinib downregulated key signaling molecules and effector proteins, including JAK2, p-JAK2, STAT3, p-STAT3, vimentin, survivin, and cyclin D1." (PMID 41476794, 2025). "Vimentin is now considered a key marker for EMT, recognized for its role in the onset of the tumor metastasis cascade." (PMID 40521243, 2025). "The metastatic TIME of the lungs displayed high levels of Vimentin+, CD44+, tumor cells and F4/80+ TAMs." (PMID 40568104, 2025). "Vimentin staining of FFPE sections containing XTCCs treated with Vorinostat revealed a slight reduction of the total tumor area, representing the bulk tumor mass as well as the invading cells." (PMID 41308994, 2025). "Compared with those in CT-26/EV cells, CT-26/FGFR4 tumor-derived CAFs exhibited higher expression levels of CAF markers, such as α-SMA, fibroblast activation protein (FAP), PDGF receptor (PDGFR), and vimentin, at both mRNA and protein levels." (PMID 40447617, 2025). "While no change in CDH1 and CDH2 expression was detected in the primary tumor tissue compared to normal colon tissue, vimentin SNAIL and TWIS showed high expression in the tumor tissue." (PMID 40566531, 2025). "In conclusion, we demonstrated that PBRM1 is a critical determinant of tumor grade and metastasis in PDAC and functions by directly regulating vimentin expression." (PMID 40454484, 2025). "Most studies have demonstrated that tumor cells express S-100, CD68, and Vimentin, whereas markers such as CK, Syn, CgA, Desmin, and pituitary hormones are typical negative, with the majority of cases also showing negativity for GFAP." (PMID 40860841, 2025). "Despite the marked cellular atypia observed, immunohistochemical examination revealed the negativity of the neoplastic tissue areas to vimentin and the positivity to cytokeratins AE1/AE3 and CK7, confirming the epithelial origin of the tumor." (PMID 41295699, 2025). "In vivo, G1 reduced liver metastasis, increased E-cadherin, and decreased vimentin and proliferating cell nuclear antigen in primary tumor tissues and increased ADAMTS1 at the tumor edge." (PMID 40867252, 2025).
tumor (continued). "Staining for vimentin and CD34 highlights the cytoplasmic projections of these characteristic tumor cells, giving them a distinct dendritic appearance." (PMID 41458523, 2025). "Western blot analysis further revealed that DGE and DOX interventions downregulated mesenchymal markers (N-cadherin and Vimentin) while upregulating the epithelial marker E-cadherin, indicating suppression of EMT in tumor cells." (PMID 40855568, 2025). "These molecules play crucial roles in cancer progression and metastasis, with vimentin being a key marker of EMT, a process that facilitates tumor cell invasion and dissemination." (PMID 39859358, 2025). "In the colon-derived cells, during the transition from a healthy to a tumor cell and then to a metastatic cell type, we observed a gradual increase in the EMT-TF genes SNAI2 and ZEB1, and in VIM, CDH5 and MMP2." (PMID 40332096, 2025). "In this study, we demonstrated for what we believe to be the first time that PBRM1 is a critical determinant of tumor grade, EMT, and metastasis in PDAC and functions by directly downregulating vimentin expression." (PMID 40454484, 2025). "IHC analysis of spheroids collected during the assay revealed effective T-cell infiltration into the 3D tumor structure (CD3), signs of T-cell activation (granzyme B, PD-1), and apoptotic tumor cells (cleaved caspase 3) while sparing CAFs (vimentin)." (PMID 39404622, 2025). "Immunohistochemical results revealed that the tumor cells expressed CD99, NKX 2.2, CD117 and vimentin positively, but negatively expressed CK, S-100, CD56." (PMID 41267976, 2025). "Circ_RPPH1 promotes tumor growth and EMT in BUC by inhibiting EIF4A3-mediated mRNA regulation, activating the EIF4A3/N-cadherin/Vimentin pathway." (PMID 40346652, 2025). "E-cadherin and Vimentin, two important proteins in epithelial-to-mesenchymal transition (EMT) were detected in the tumor tissue." (PMID 40302791, 2025). "The tumor cells showed expression of PAX8, CA9, AMACR/P504S, Vimentin, CK7, CD10, FH, INI1(SMARCB1) and ELOC(TCEB1), and ELOC was mainly located in the nucleus." (PMID 41306531, 2025). "WB assays also confirmed that treatment with rhSFRP1, rmSFRP1, and CM from CAF-Sfrp1 enhanced tumor stemness and EMT activity, as evidenced by upregulation of CD44, CD133, ZEB1, Vimentin, and N-cadherin, along with the downregulation of E-cadherin." (PMID 40225580, 2025). "In vivo, co-injection of SCC25 cells with GFs significantly promoted tumor growth and stromal CAF marker expression, whereas CXCR2 knockdown in GFs led to a ~ 40% reduction in tumor volume and reduced αSMA/vimentin-positive CAFs." (PMID 40490643, 2025). "Immunoblotting analyses showed that the CSNK1D expression levels were correlated with the levels of E-cadherin, N-cadherin, Vimentin, BCL2, and Bax in the tumor tissues of nude mice." (PMID 41353440, 2025). "Using qRT-PCR, we observed a decrease in E-cadherin and an increase in mesenchymal markers such as Slug, N-cadherin, vimentin, ZEB1, and ZEB2 in LNCaP cells treated with periprostatic tumor fat medium, indicating epithelial–mesenchymal transition." (PMID 40437336, 2025). "Stress-induced proteins, such as vimentin, contribute to EMT, increasing tumor cell motility and adhesion strength through activation of the Rac pathway, as observed in MCF-7 cells." (PMID 40647432, 2025). "IHC analysis corroborated these findings, with reduced staining intensity for mesenchymal markers (Vimentin, N-cadherin, ZEB-1) and increased intensity for E-cadherin observed in ARPC1B-knockdown tumor tissues (Fig. A7C)." (PMID 41050079, 2025). "When combined with gemcitabine, EGCG suppressed tumor migration and invasion by downregulating the zinc finger E-box binding homeobox 1 (ZEB1), β-Catenin, and vimentin pathways, while inhibiting Akt and EMT pathways." (PMID 40918466, 2025).
tumor (continued). "Immunohistochemically, vimentin, SMA, and P16 were diffuse positive in tumor cells, whereas desmin, CK, P40, P63, CK5, HMB45, MyoD1, myogenin, S100, and SOX10 were all negative." (PMID 39872225, 2025). "First, Mon was found to play an anti‐tumor role in HCC cells by inhibiting cell proliferation and invasion, elevated the expression of E‐cadherin, and decreased N‐cadherin and Vimentin expression." (PMID 40439491, 2025). "In our case the tumour cells reacted positively with CD31, vimentin, and FLI-1, which supports the endothelial origin of the tumour." (PMID 40542819, 2025). "Immunohistochemical staining revealed diffuse KRT7, vimentin, PAX8, e-cadherin, SDHA, SDHB and fumarate hydratase expression in tumor cells." (PMID 39980061, 2025). "Composite indices were generated to quantify immune suppression (PD-L1, PD-1, LAG3, FOXP3, IDO, CD68), CAF activation (SMA, Vimentin), endothelial activation (CD31), and tumor proliferation (Ki67)." (PMID 41595458, 2025). "In the eight experimental groups, SERPINA1 knockdown reversed ITGB3 overexpression-induced effects, normalizing PCNA/Vimentin elevation and E-cadherin suppression (P < 0.05), establishing ITGB3 as the primary effector of SERPINA1-mediated tumor progression." (PMID 41467954, 2025). "Vimentin (VIM), an intermediate filament protein, was reported to be closely related to tumor invasiveness and prognosis, making it a potential tumor biomarker." (PMID 40649778, 2025). "Several muscle cell markers such as vimentin, SMA, and desmin can be used to identify the tumor originating from mesenchymal tissues as an auxiliary diagnosis." (PMID 40224630, 2025). "HGESS tumor cells display cellular atypia, increased mitosis, infiltration, and necrosis with immunohistochemical results showing that most tumor cells are positive for CD10, vimentin, PR, and ER." (PMID 40678607, 2025). "Circulating tumor cell subsets expressing cancer stem cell markers (CD90, epithelial cell adhesion molecule; CD133, vimentin) were assessed using multiparametric flow cytometry and compared with alpha-fetoprotein and des-gamma-carboxy prothrombin." (PMID 40940925, 2025). "MCPIP1 levels were lower in the tumor tissues of the MCPIP knockdown group, whereas vimentin, N‐cadherin, and E‐cadherin levels were higher than those of the control group." (PMID 40874680, 2025). "Among them, VIM and HOPX are frequently silenced by promoter hypermethylation in other malignancies, and HOPX functions as a potent tumor suppressor." (PMID 41228323, 2025). "The tumor was composed of atypical spindle cells that were partly positive for cytokeratin AE1/3, CAM5.2, and vimentin and scattered osteoclast-like multinucleated giant cells that were positive for CD68." (PMID 40230762, 2025). "IHC analysis of the tumor tissues revealed decreased expression of CD31, Vimentin, and N-Cadherin in RGS3-knockdown tumors." (PMID 40456746, 2025). "STAT3 is an important transcription factor in tumor progression, and its activation is pivotal in regulating the expression of EMT-related genes/proteins, such as Twist, Vimentin, Snail, MMPs, and ZEB1, essential proteins in metastasis." (PMID 39412616, 2025). "Vimentin, which is a canonical mesenchymal marker involved in DDP-induced tumor chemotherapy resistance 47, 48, was verified as an interacting protein of CCND3 by Co-IP and immunofluorescence assays." (PMID 39781469, 2025). "Immunohistochemical staining demonstrated that tumor tissues from the PAQR5 knockdown group exhibited reduced Ki-67 and vimentin expression, alongside increased E-cadherin staining, compared to controls (P < 0.05)." (PMID 40336138, 2025). "The identification of gene co-expression modules containing classical EMT markers (e.g., VIM, ZEB1, SNAI2) alongside ECM-related genes (COL1A1, FN1, SPARC, LOX) underscores a tightly coordinated interaction driving tumor cell plasticity and invasion." (PMID 40943497, 2025).
tumor (continued). "When all ESCA cells were xenotransplanted subcutaneously into BALB/c-nu mice, they developed into tumors that resembled the original tumor with positive AE1/3 and Vimentin in immunohistochemical staining." (PMID 40455147, 2025). "IHC results obtained from xenograft tumor sections showed decreased levels of DEC1, ZEB1, N-cadherin, Vimentin, Snail1 and Ki67 in DEC1 KD tumor tissue compared to control sections." (PMID 40133270, 2025). "IHC of orthotopic tumor tissues from nude mice corroborated these findings: TCN1-knockdown tumors exhibited reduced N-cadherin and vimentin expression, but increased E-cadherin expression." (PMID 41154358, 2025). "AKT/GSK-3β activation promotes tumor growth, metastasis, and EMT formation (the expression of EMT markers such as Vimentin, and Snail)." (PMID 40265472, 2025). "Using bulk RNA sequencing and immunofluorescence (IF) for EMT (E‐cadherin and vimentin) and lymphocyte markers (CD3, CD8, FOXP3), we analyzed pre‐ and post‐NAC tumor samples from 100 early‐BC patients treated with NAC." (PMID 39912409, 2025). "Immunohistochemically, vimentin, smooth muscle actin (SMA), and P16 were diffuse positive in tumor cells, whereas desmin, cytokeratin (CK), P40, P63, CK5, HMB45, MyoD1, myogenin, S100, and SOX10 were all negative." (PMID 39872225, 2025). "We observed a significant low positive Pearson correlation coefficient between vimentin and CD3 + CD8‐FOXP3‐lymphocytes in the stromal area and the tumor cluster (r = 0.31 (P‐val = 0.002) and r = 0.32 (Pval‐0.001), respectively)." (PMID 39912409, 2025). "↓cathepsin S levels → ↓ fibronectin, vimentin, Rho A expression → EMT reversal, reduced invasiveness, and tumor regression." (PMID 40761486, 2025). "EMT-inducing transcription factors, such as TWIST1 and SNAIL1, not only repress E-cadherin but also drive tumor angiogenesis through the regulation of MMP9, N-cadherin, and vimentin." (PMID 40647432, 2025). "This leads to the repression of E-cadherin and the promotion of Vimentin expression, thereby inducing EMT and enhancing tumor cell migration and invasion." (PMID 41019994, 2025). "The expression levels of Vimentin in M13HS-2 and M13HS-8 tumor hybrids were comparable to those of HS578T-Hyg cells." (PMID 40471394, 2025). "Most tumor specimens showed positivity for desmin, smooth muscle actin (SMA), vimentin, and caldesmon." (PMID 39329869, 2024). "When co-cultured with tumor cells, it was observed that tumor cells located near CAFs with reduced COL5A1 expression also exhibited decreased Vimentin expression." (PMID 38987529, 2024). "Vimentin (VIM) staining in organoid sections, as well as in tumor sections demonstrated a marked reduction in vimentin expression, specifically in cancer cells from both DUSP1−/+ clones, validating the previous results." (PMID 38951654, 2024). "Tumor cells were immersed in a dense stromal ECM, as suggested by the relevant expression of Desmin, αSMA, Collagen I, PDGFRα and Vimentin." (PMID 38338669, 2024). "The primary T14 tumor cells were also strongly positive for the RB markers synaptophysin and TFF1 as well as for vimentin." (PMID 39695086, 2024). "In our study, tumor cells showed strong immunoreactivity to EMA and vimentin in the inflammatory background and diffuse infiltration of plasma cells and lymphocytes, which are typical LPM manifestations." (PMID 38254159, 2024). "In a case study of TCCBD, the tumor cells were immunohistochemically positive for CD10, CAM5.2, and vimentin." (PMID 38672619, 2024). "Immunohistochemical assessment of E-cadherin, β-catenin, Vimentin, ZEB-1 and Ki-67 was performed in each tumor and a semiquantitative estimation of the percentage of expression was fulfilled on the best marking area at high of the tumor invasion front." (PMID 39388828, 2024). "Immunohistochemical analysis demonstrated strong positive expression of vimentin (VIM) and CD68 in tumor cells." (PMID 38903727, 2024).